MTOR (mechanistic target of rapamycin kinase)
Diseases named in the same sentence as MTOR in open-access papers (continued):
Sharing a sentence is not in itself a finding about the gene and the disease.
prostate carcinoma (continued). "The PI3K/AKT/mTOR pathway is over-activated in many human cancers, including prostate cancer, and has emerged as a target for small molecule therapies." (PMID 28915623, 2017). "In prostate cancer patients, there was a statistically significant decrease of mTOR and PS6K expression after hormonal deprivation therapy." (PMID 28615679, 2017). "We have recently shown that in PC3 and DU145 prostate cancer cells mTOR-mediated SK1 expression plays a key role in cancer cell chemoresistance." (PMID 28615679, 2017). "To address intra-tumour heterogeneity and differ-ences between patients, we investigated the role of PI3K/AKT/mTOR signalling in a range of prostate cancer primary cultures and PDXs." (PMID 28915623, 2017). "Meanwhile, reduction in 5-hmC by miR-29a/b activated prostate cancer-related key pathways such as mammalian target of rapamycin (mTOR) and AR, indicating significant oncogenic roles of miR-29 in prostate cancer progression." (PMID 28783103, 2017). "This was performed by targeting the pathway with AKT and mTOR inhibitors in prostate cancer cell lines, primary cell cultures and a ‘near-patient’ xenograft." (PMID 28915623, 2017). "The PC-3 prostate cancer cell line used in this current study also harbors a PTEN-null mutation resulting in constitutive activation of Akt and its downstream target mTOR." (PMID 28903409, 2017). "Accumulation of Phlpp1 and Deptor with corresponding inactivation of Akt/mTOR was also detected in Sag-null prostate cancer tissues." (PMID 27955654, 2016). "With further analysis, we found that within the marrow the osteoblastic niche controls conversion of disseminated prostate cancer cells to CSCs through the GAS6/Mer/mTOR pathway." (PMID 27172799, 2016). "In prostate cancer, several findings have illustrated that PI3K/AKT/mTOR pathway upregulation resulting from PTEN loss is associated with the development of CRPC." (PMID 27323416, 2016). "In summary, phosphorylated mTOR, a marker of PI3K pathway activation, is associated with a favorable prognosis in primary prostate cancer." (PMID 27096957, 2016). "While cancer pathways contained prostate cancer, thyroid cancer, chronic myeloid leukemia, melanoma, glioma, ErbB signaling pathway, and mTOR signaling pathway." (PMID 27917343, 2016). "The Phosphoinositide 3-kinase (PI3K)- AKT- mammalian target of rapamycin (mTOR) pathway stimulates cell survival, growth and differentiation and is often activated in prostate cancer." (PMID 27096957, 2016). "To exemplify this, we examined the results of the differential translation analysis with the PC3 data, to pursue novel biological insights into the translational dysregulations involved in mTOR inhibition by PP242 in prostate cancer cells." (PMID 27041671, 2016). "In this report, we evaluate a potential correlation of mTOR pathway activation with biochemical relapse-free survival in primary prostate cancer." (PMID 27096957, 2016). "The Akt/mammalian (or mechanistic) target of rapamycin (mTOR) signaling pathway is frequently hyperactivated in a wide assortment of human solid tumors including prostate cancer." (PMID 26625315, 2016). "It is unexpected that high p-mTOR, a marker of activated PI3K signaling, is associated with favorable prognosis in prostate cancer." (PMID 27096957, 2016). "This provides a plausible explanation why mTOR inhibitors proved unsuccessful in prostate cancer trials." (PMID 27096957, 2016). "The loss of phosphatase and tensin homologue (PTEN) deleted on chromosome 10 is prevalent in the majority of advanced prostate cancers leading to constitutive activation of the phosphoinositide 3-kinase (PI3K)/Akt/mammalian target of rapamycin (mTOR) pathway." (PMID 27821815, 2016). "We found that GAS6 triggered mTOR signaling in prostate cancer, with increases seen in both mTORC1 and mTORC2, and these were diminished by the mTORC1 inhibitor rapamycin and the dual mTORC1/2 inhibitor pp242." (PMID 27172799, 2016).
prostate carcinoma (continued). "Surprisingly, the mTOR signaling pathway is activated specifically in prostate cancer patients with a favorable outcome." (PMID 27096957, 2016). "Overall, in our paper, we provide the first mechanistic link between mTOR inhibition and docetaxel resistance in prostate cancer implicating the regulation of HIF-1α/SK1 pathways." (PMID 27821815, 2016). "It has already been reported that silencing mTOR decreases prostate cancer cell proliferation and colony formation." (PMID 27491285, 2016). "This is not exceptional, and except for some combined therapies that include PI3K, Akt, mTOR inhibitors, e.g., for breast and prostate cancer subtypes, treatment of solid tumors with these inhibitors has been often ineffective." (PMID 27835880, 2016). "We found that the Sag deletion suppressed the progression of prostate cancer induced by Pten-loss with mechanism involving accumulation of Phlpp1 and Deptor to inhibit PI3K/AKT/mTOR signaling pathway." (PMID 27955654, 2016). "Prostate cancer cells were treated with PA (20 μM) and the effect on mTOR signaling pathway and induction of autophagy was evaluated." (PMID 26683363, 2016). "Abnormal activation of the PTEN/AKT/mTOR pathway is the most frequent event in prostate cancer and it is, therefore, important to identify the cofactors modulating prostate cancer progression in the context of altered PTEN/AKT/mTOR signaling." (PMID 27955654, 2016). "Cells treated with inhibitors of PI3K and mTOR or transiently transfected with dominant negative AKT or PI3K have been reported to inhibit HIF-1α expression in human prostate cancer cell lines." (PMID 26882567, 2016). "For example, miR-96 can promote or inhibit autophagy by principally inhibiting mTOR or ATG7 depending on the expression levels of miR-96 in prostate cancer cells under hypoxia." (PMID 27803889, 2016). "The PI3K/Akt/mTOR signaling pathway also inhibits autophagy in many types of human cancer cells, including ovarian cancer, HepG2, prostate cancer, gastric cancer, and colorectal cancer cells." (PMID 27863375, 2016). "Our studies show that PA negatively regulated mTOR signaling in prostate cancer cells in an AMPK dependent manner." (PMID 26683363, 2016). "Collectively, our results suggested that SAG knockdown triggers accumulation of PHLPP1 and DEPTOR to inactivate the AKT/mTOR axis, leading to observed suppression of growth and survival in prostate cancer cells." (PMID 27955654, 2016). "mTOR pathway activation is reported in prostate cancer, but clinical trials testing efficacy of mTOR inhibitors were unsuccessful." (PMID 27096957, 2016). "While in this study the evidence of using combination therapy is indirect (both therapies were not administered together), it encourages further investigation of mTOR inhibitors in prostate cancer." (PMID 27821815, 2016). "Recent research has shown that mTOR inhibition using the specific inhibitor RAD001 increased radiosensitivity of prostate cancer cells by inducing autophagic cell death." (PMID 27694690, 2016). "For instance, hypoxia induced miR‐96 expression can stimulate autophagy via inhibiting MTOR in prostate cancer cells." (PMID 26990493, 2016). "It is conceivable that mTOR phosphorylation in prostate cancer selectively plays a role in tumor onset and development rather than affecting disease progression." (PMID 27096957, 2016). "Several studies indicate that mTOR inhibition is a valid strategy for docetaxel sensitization in prostate cancer." (PMID 27821815, 2016). "To date, most of the prostate cancer-specific experience targeting this pathway comes from studies testing allosteric mTOR inhibitors, with these studies all generally failing to demonstrate sufficient activity to warrant further study." (PMID 26566796, 2015). "In the present study we investigate the effects of the multikinase inhibitor sorafenib in a genetically engineered mouse model of prostate cancer and explore the rational combination with the mTOR inhibitor everolimus." (PMID 25953027, 2015).
prostate carcinoma (continued). "The PI3K/AKT/mTOR pathway is over-activated in several cancers including prostate cancers and much effort has been devoted to its inhibition." (PMID 25834103, 2015). "Inhibition of PI3K by LY294002 or other PI3K inhibitors and mTOR by rapamycin have been demonstrated to induce G1 cell cycle arrest in the prostate cancer cells and other human malignances." (PMID 26506516, 2015). "Further, it is known that mTOR plays a crucial role in the progression of prostate cancer to CRPC by influencing the androgen signaling pathway." (PMID 26251134, 2015). "It has been shown that key signaling transduction pathways such as the Akt/mTOR pathway affect cancer cell survival and are highly activated in prostate cancer." (PMID 26317998, 2015). "Previously, we demonstrated that CXCL16/CXCR6 chemokine axis induces prostate cancer progression by the AKT/mTOR signaling pathway." (PMID 25909173, 2015). "CamKII is actually known to activate AKT/mTOR pathway and was demonstrated to down-regulate Mcl-1 in prostate cancer cells." (PMID 25627260, 2015). "For one, allosteric mTOR inhibitors only inhibit mTORC1 activity, and evidence supports mTORC2 as being an important activator of Akt in prostate cancer cells." (PMID 26566796, 2015). "Currently there are two clinical trials investigating PI3Kβ inhibitor GSK2636771 (NCT02215096) and pan-PI3K/mTOR inhibitor LY3023414 (NCT02407054) in combination with enzalutamide in metastatic castration-resistant prostate cancer patients." (PMID 26506516, 2015). "Mithramycin has been found to induce apoptosis by regulating the mTOR/Mcl-1/tsBid pathway in androgen-independent prostate cancer cells." (PMID 26484141, 2015). "The role of SFN in regulation of the translational machinery in hypoxia has not been thoroughly investigated so far, however, its inhibitory effect on mTOR pathway was shown in PC3 prostate cancer cells cultivated under standard conditions." (PMID 25955133, 2015). "The PI3K/AKT/mTOR pathway plays a crucial role in the development of prostate cancer and transformation to CRPC." (PMID 25953027, 2015). "For example, the pan-AKT inhibitor AZD5363 has recently been reported to induce autophagy in prostate cancer cells, by down-regulating the mTOR pathway." (PMID 24946858, 2014). "Recent studies in breast and prostate cancer demonstrate that this resistance can be reversed with the addition of an mTOR inhibitor." (PMID 25104960, 2014). "In conclusion, the up-regulation of miR-96 in response to hypoxic stress in prostate cancer cells inhibited MTOR, enhanced autophagy, and maintained cell survival." (PMID 25333253, 2014). "To explore this idea, we selected two cell lines, MDA-MB-231 and PC-3 prostate cancer cells, for their known sensitivity to inhibition of either eIF4A or mTOR." (PMID 25273840, 2014). "We have now extended these studies to evaluate the impact of MSeA on REDD1 (an mTOR inhibitor) in inducing cell death of invasive prostate cancer cells in hypoxia." (PMID 24515947, 2014). "In this study, we have investigated the function of miR-96 in the regulation of autophagy in prostate cancer cells under hypoxia, and found that miR-96 regulates autophagy under hypoxia via targeting MTOR and ATG7." (PMID 25333253, 2014). "DU-145 prostate cancer cells were treated with insulin-like growth factor (IGF) to activate the Akt-mTOR cascade or with the HDAC-inhibitor valproic acid (VPA) to induce histone H3 and H4 acetylation (aH3, aH4)." (PMID 24779401, 2014). "We found that the miR-96 level was reversely correlated with the protein levels of ATG7 and MTOR (p < 0.05), which indicate that miR-96 regulates ATG7 and MTOR in prostate cancer tissues." (PMID 25333253, 2014). "Anthocyanin, a flavonoid, was demonstrated to activate AMPK, leading to reduction in mTOR phosphorylation and inhibiting cancer cell growth; Fisetin induces apoptosis by activating AMPK and suppressing mTOR in non-small lung cancer and prostate cancer cells." (PMID 25295069, 2014).
prostate carcinoma (continued). "The translational control pathway ‘EIF2 Signaling’ was enriched in four tumors, with three-quarters also overexpressing genes involved in ‘mTOR Signaling’, a druggable pathway of considerable potential in prostate cancer." (PMID 25155515, 2014). "Previous studies have reported that miR-99a can inhibit mTOR expression by directly targeting its 3′-UTR in numerous human cancers including prostate cancer cells, childhood adrenocortical tumor cells, and c-Src-transformed cells." (PMID 24637915, 2014). "Both Akt and mTOR are two important PI3K targets that are frequently activated in human primary prostate cancer specimens, as evidenced by increased phosphorylation of both Akt and S6RP, a downstream target of mTOR." (PMID 24062990, 2013). "We first investigated the expression of distinctive mTOR complex components in several lines of human colon and prostate cancer cells in which Src is upregulated." (PMID 24244675, 2013). "Conclusively, combination of mTOR/Erk/Hsp90 inhibits metastatic capacity of prostate cancer via Slug inhibition." (PMID 24130883, 2013). "Other agents targeting mTOR in prostate cancer include the dual PI3K-mTOR inhibitor, BEZ235, which has shown potent in vitro radiosensitization both in normoxic and hypoxic conditions." (PMID 23863691, 2013). "Upon treatment of PC3 cells with carnosol we observed a dose-dependent decrease in phosphorylation of mTOR protein thereby leading to inhibition of prostate cancer in vitro." (PMID 23531917, 2013). "Drugs, including antibodies, targeting the insulin-like peptides signalling through the PI3K/Akt/mTOR pathway are currently in various clinical trials in breast and prostate cancers." (PMID 24237932, 2013). "Given the high prevalence of PTEN loss/inactivation and the importance of this pathway to tumor behavior and response to radiation, inhibition of mTOR activity has been an attractive therapeutic target in prostate cancer." (PMID 23863691, 2013). "Activation of AMPK by B-DIM results in the suppression of its downstream target mTOR, down-regulation of AR expression and induction of apoptosis in both androgen-sensitive LNCaP and androgen-insensitive C4-2B prostate cancer cells." (PMID 23056607, 2012). "Here we investigated both the effects of mTOR inhibition alone, as well as in combination with AR blockade, in models of prostate cancer." (PMID 22614157, 2012). "Compensatory regulation between the AR and mTOR pathways has emerged as a key mechanism in the pathogenesis of prostate cancer." (PMID 22614157, 2012). "Consistent with this, we found mTOR signaling to be elevated in PTEN−/− prostate cancer lines relative to PTEN+/+ lines, and that PTEN−/− lines exhibit greater sensitivity to ridaforolimus in vitro." (PMID 22614157, 2012). "Curcumin and fisetin also were shown to modulate the expression of mTOR, Rictor and Raptor in colorectal and prostate cancer cells respectively." (PMID 22952709, 2012). "This provides a clear biological rationale for the blockade of mTOR activity as a potential therapeutic point of intervention for prostate cancer." (PMID 22614157, 2012). "Dual inhibition of the AR and mTOR signaling pathways provided further benefit with the ridaforolimus-bicalutamide combination producing synergistic antiproliferative effects in prostate cancer cells in vitro when compared with each agent alone." (PMID 22614157, 2012). "Taken together, our results identify a potential molecular predictor of response to ridaforolimus treatment in prostate cancer, and also support the possible therapeutic utility of mTOR blockade for treating this disease." (PMID 22614157, 2012).
prostate carcinoma (continued). "Ridaforolimus treatment inhibited the proliferation of all six prostate cancer cell lines examined with the greatest sensitivity associated with loss of PTEN and elevated AKT/mTOR pathway activity." (PMID 22614157, 2012). "In summary, we have shown that the mTOR inhibitor ridaforolimus exhibits robust antiproliferative activity in preclinical models of prostate cancer, alone and in combination with an antiandrogen." (PMID 22614157, 2012). "Since Akt plays a central role in the regulation of both NF-κB and mTOR we evaluated the significance of Akt inhibition in killing of prostate cancer cells by CDDO-Me." (PMID 21961053, 2011). "In the first phase of this study we analyzed 1,084 SNPs in 67 genes involved in the mTOR pathway in 815 prostate cancer cases and 1,266 matched controls." (PMID 21373201, 2011). "Since increased MYC expression is an early feature of many human prostate cancers, these data have implications for treatment of human prostate cancers with PI3K-pathway alterations using mTOR inhibitors." (PMID 21394210, 2011). "Given the high prevalence of PI3K/Akt/mTOR activation resulting from loss of PTEN expression, a strong rationale exists to use mTOR inhibitors in prostate cancer." (PMID 24212820, 2011). "In another study, Nkx3.1;Pten mutant mice were used as a preclinical model for the effects that inhibition of both Ras/Raf/MEK/ERK and Ras/PI3K/PTEN/Akt/mTOR pathways would have on hormone-dependent and -independent prostate cancer growth." (PMID 21422497, 2011). "CDDO-Me inhibited the growth of murine TRAMPC-1 prostate cancer cells by inducing apoptosis through the inhibition of antiapoptotic p-Akt, p-mTOR and NF-κB." (PMID 21961053, 2011). "Several studies have shown that treatment of prostate cancer cells with sulforaphane and inhibition of mTOR ( target of rapamycin) induces autophagy and increased response to irradiation." (PMID 22039439, 2011). "CDDO-Me inhibited the prosurvival Akt, NF-κB and mammalian target of rapamycin (mTOR) signaling proteins in prostate cancer cells." (PMID 21799944, 2010). "Recent studies in prostate cancer model systems have shown that cyclin D1 accumulates after androgen stimulation as a result of mTOR activation and resultant enhancement of cyclin D1 mRNA translation." (PMID 17375037, 2007). "There is now overwhelming evidence implicating the PI3K/AKT/mTOR pathway as a regulator in the malignant progression of prostate cancer." (PMID 16983403, 2006). "Functional loss of PTEN (which is the negative regulator of PI3K) is thought to occur in up to half of all prostate cancers, and is associated with increased activation of AKT and the downstream kinase mTOR, which is involved in regulating protein synthesis." (PMID 16983403, 2006). "However, the efficacy of rapamycin and other mTOR inhibitors in prostate cancer remains a subject of debate." (PMID 40723786, 2025). "Therefore, targeting PI3K or PI3K/AKT/mTOR signaling pathway is considered a promising therapeutic option for treating prostate cancers." (PMID 40427108, 2025). "According to several studies, the PI3K-Akt-mTOR pathway may be a significant factor in prostate cancer as a therapeutic target and/or a predictive biomarker for the development, and behavior of the illness." (PMID 39900661, 2025). "Moreover, the complete mTOR inhibition by ATP site blockade reprograms this gene expression prevents prostate cancer invasion and metastasis." (PMID 39941741, 2025). "Thus, SMC4 potentially regulates the growth and metastasis of metastatic prostate cancer cells through the Rheb/mTOR pathway." (PMID 40278414, 2025). "Moreover, cuproptosis improved chemosensitivity to docetaxel in prostate cancer cell lines by hindering autophagy via the dihydrolipoamide S-acetyltransferase (DLAT)/mammalian target of rapamycin (mTOR) pathway." (PMID 40066457, 2025).